STAT3 (signal transducer and activator of transcription 3)
Diseases named in the same sentence as STAT3 in open-access papers (continued):
Sharing a sentence is not in itself a finding about the gene and the disease.
tumor (continued). "SHP-1 is a nonreceptor protein tyrosine phosphatase (PTP) that notably has tumor-suppressive potential due to its negative regulation of STAT3 oncogenic signaling during tumor progression." (PMID 31485222, 2019). "This suggests that tumor cells can dampen DCs differentiation through an autocrine activation of STAT3 by IL-6." (PMID 31480382, 2019). "Napabucasin (BBI608), a small molecule inhibitor proposed to interfere with STAT3 signaling, has been shown to inhibit stem-like tumor cells in ad-hoc designed preclinical models." (PMID 31143708, 2019). "Myeloid progenitors can also be shifted toward MDSC differentiation and away from DCs and macrophages by tumor-derived soluble factors that induce STAT3 activation, leading toward the MDSC phenotype by suppression of protein kinase C βII." (PMID 31921140, 2019). "The effective regulation by SPG-56 of the expression of metastasis-related proteins MMP2, MMP9, VEGF, Occludin, Claudin and STAT3 further confirmed the inhibition by SPG-56 of tumor metastasis." (PMID 30651572, 2019). "IL-6 then activates the signal transducer and activator of transcription 3 (STAT3) pathway in immune cells, stromal cells, and tumor cells, which supports overall immune escape of cancer cells." (PMID 31409361, 2019). "A recent study has shown that acetylated STAT3 is highly elevated in TNBC, causing the methylation and inactivation of tumor-suppressor gene promoters." (PMID 31088482, 2019). "Cytokines and growth factors secreted by tumor and stromal cells regulate the differentiation of myeloid progenitor cells through a variety of transcription factors, of which the STAT3 plays a critical role." (PMID 31395859, 2019). "Stattic, an inhibitor of STAT3, combined with metformin can inhibit tumor initiating cells in the brain by reducing STAT3-phosphorylation." (PMID 31775797, 2019). "When performing analyses of randomly chosen tumor areas (excluding the tumor border and necrotic areas), we found phospho-Stat3 (Tyr705) slightly reduced." (PMID 30857197, 2019). "Tumor and immune cells expressing STAT3 develop sophisticated interactions to overall support an immunosuppressive tumor environment that propels metastatic progression." (PMID 31569642, 2019). "In the case, PLK1, BCL2, and STAT3, three important proteins with high relevance in tumor growth, were selected." (PMID 31888119, 2019). "Of these molecules, IL-1β, IL-6, TNF-α, and IL-4 promote the phosphorylation of downstream proteins, e.g., NF-κB and STAT3, which then lead to inflammation, tumor proliferation, and prevention of apoptosis in cancer." (PMID 31781219, 2019). "In response to the microenvironmental factors, triggered by inflammation or hypoxia, STAT3 signaling regulates the activity of HIF1α, the central switch of tumor angiogenesis." (PMID 31234597, 2019). "Conventional methods to detect STAT3 pathway activation are by immunohistochemistry where pSTAT3-specific antibodies are used on frozen or paraffin-embedded tumor sections." (PMID 31399589, 2019). "For PDAC, in an experimental set up, a critical role for STAT3 was seen, which, however, appears to be operative in early events of tumor manifestation." (PMID 31540511, 2019). "STAT3 signaling is generally considered the pathway in tumor cells that responds to the inflammatory TME." (PMID 30927928, 2019). "In low oxygenated cells, HIF-1α, mTOR, TGFβ and Stat3 levels were shown to increase CD133 expression in tumour cells, promoting GSC formation and proliferation." (PMID 31690341, 2019). "Recent findings have established STAT3 as a powerful regulator of tumor-mediated immune suppression." (PMID 31088482, 2019).
tumor (continued). "Even under these conditions, a high SP1-S3 score was still significantly predictive of poor prognosis, supporting the idea that SP1 and STAT3 can functionally cooperate to enhance tumor aggressiveness independently of the tumor subtype." (PMID 30654518, 2019). "The activation of JAK can promote robust STAT3 phosphorylation in different tumor cell lines, including MM." (PMID 31878046, 2019). "Martensen also showed that breast tumors in female PyMT mice receiving a high folic acid diet displayed significantly increased tumour volumes along with STAT3 activation, compared to mice receiving a normal diet." (PMID 30867007, 2019). "Phosphorylation of Stat3 and its oncogenic activity was demonstrated to be constitutive due to both cell intrinsic and tumor microenvironment (TME) cross talk in PDAC." (PMID 31277415, 2019). "By assessing intrinsic and extrinsic tumor characteristics of these groups, we observed three STAT3 patterns: a T-STAT3 dominant pattern, a E-STAT3 dominant pattern, and an E-STAT3 depleted pattern." (PMID 31796877, 2019). "Beyond its impact on tumor cells, STAT3 has an important role in restricting immune cell functions and producing immunosuppressive factors." (PMID 31684144, 2019). "ABCC3-mediated regulation of PDAC cell proliferation and tumour growth in vivo was demonstrated and was shown to be conferred by upregulation of STAT3 signalling and regulation of apoptosis." (PMID 31378204, 2019). "In conclusion, we have shown that we can distinguish between tumor and environmental STAT3 activity in gene expression studies and that this distinction leads to biological and clinical insights." (PMID 31796877, 2019). "The revamping of immunity support for better tumor control by targeting IL-6/STAT3 signaling in EOC." (PMID 31861720, 2019). "Western blot assay was used to evaluate S1PR1 and p-STAT3 expression in MDSCs after separation from the liver and tumor by magnetic antibody." (PMID 31534132, 2019). "The expression level of STAT3 protein in tumor tissues of patients with STAT3 rs1053004 locus GG genotype was significantly higher than in patients with type GA, and it was the lowest in patients with type AA." (PMID 31270251, 2019). "MDSCs from tumor-bearing mice present high levels of phosphorylated STAT3, compared with immature myeloid cells from naive mice." (PMID 31480382, 2019). "NF-κB and STAT3 are two major factors controlling tumor inflammation, angiogenesis and invasiveness." (PMID 30781521, 2019). "To further explore the potential roles of STAT1 and STAT3 in IFN-g-induced PD-L1 expression on tumor cells, we knocked down their expression with specific siRNAs." (PMID 31730010, 2019). "IHC staining shows strong SHP-1 correlation with p-STAT3 expression in normal liver and vice versa in human tumor samples." (PMID 31619257, 2019). "As an example that the comparisons of transcriptomes of premalignant cells with tumor cells and the use of metformin can identify stemness factors in cancer cells, we knocked down Stat3 in NB508 PDAC cells." (PMID 30614183, 2019). "Inhibition of ERBB or STAT3 prevents tumor growth in xenograft models and restores MHC class I expression, suggesting a chemo-immunotherapeutic strategy to save Tasmanian devils." (PMID 30645971, 2019). "TAMs-derived IL6 activated the JAK2/STAT3 pathway, and activated STAT3 transcriptionally inhibited the tumor suppressor miR-506-3p in CRC cells." (PMID 30927925, 2019). "We also show that biological insights can be obtained utilizing TME- and tumor-specific STAT3 activity inferences." (PMID 31796877, 2019). "Our data showed that HFD feeding increased tumor size, STAT3 phosphorylation (Y705), and PA levels in the xenograft tissues of the PCa-bearing mouse model." (PMID 31474764, 2019). "By inhibiting STAT3 phosphorylation, AG-490 was shown effective in reducing osteolysis and tumor growth in the metastatic niche." (PMID 31040267, 2019).
tumor (continued). "Consistently, we found that Akirin2 overexpression upregulated, whereas endogenous Akirin2 knockdown eliminated VEGFA expression and angiogenesis through the IL-6/STAT3 signaling pathway, and thus facilitated tumor growth, invasion, and metastasis." (PMID 30886152, 2019). "Signal transducer and activator of transcription 3 (STAT3) is an oncogene playing critical roles in tumour development, angiogenesis, and metastasis." (PMID 31261935, 2019). "Alternatively, HBx downregulates Let-7 that can also activate STAT3 signaling by failing to modulate the expression of inflammatory cytokines, to influence miRNA-mediated suppression of key tumor suppressors (pathway 13)." (PMID 31771261, 2019). "Key oncogenic signaling such as NF-κB and STAT3, which drive tumor progression and promote a cancer stem cell phenotype in malignancies that include gliomas, were activated following SM treatment." (PMID 30854231, 2019). "Although it is not clear that the NB TIC in this study is the same as the CD114+ cell in previous studies, it does provide compelling evidence for the presence of a STAT3-expressing NB tumor-initiating cell." (PMID 31803140, 2019). "NEAT1 sponges miR-361 to initiate a prometastatic network involving STAT3 signaling, prometastatic genes and tumor microenvironment-related genes." (PMID 31287002, 2019). "An increase in S1PR1 in CD4+ T-cells promotes STAT3 activation and JAK/STAT3-dependent Treg tumor migration, whereas STAT3 ablation in T-cells diminishes tumor-associated Treg accumulation and tumor growth." (PMID 31480382, 2019). "In summary, our results suggest that DFTD tumor cells exhibit an ERBB-dependent constitutive activation of STAT3 in a positive feedforward loop." (PMID 30645971, 2019). "Although a B7-H3 receptor has not been found, B7-H3 can regulate the survival, proliferation, and glycolysis of tumor cells through various signaling pathways, including hypoxia-inducible factor-1α, nuclear factor-κB, Stat3, and phosphoinositide 3-kinase." (PMID 31998637, 2019). "Together, NFκB and STAT3 have the capability to regulate apoptosis, angiogenesis, and tumor invasion thus enabling resistance toward immune surveillance." (PMID 31555295, 2019). "To further verify the dependency of Tu2449 cells on Stat3 in a more complex cell culture system, we generated Tu2449 tumor spheroids, which resemble an in vivo situation more closely with regard to gradient access to oxygen, nutrients, as well as therapeutics." (PMID 30857197, 2019). "Factors in the TME, including pH, oxygen supply, immune surveillance, fibroblasts and ECM, can respond to drugs and initiate signalings to activate resistance-associated pathways in tumor cells, such as the AKT, mTOR, NF-κB, and STAT3 pathways." (PMID 30927928, 2019). "Our findings also showed that blocking ITGA2 improved tumor immune responses by decreasing the phosphorylation level of STAT3 and suppressing PD-L1 expression in vivo." (PMID 31818309, 2019). "Tumor‐infiltrating immune cells, including myeloid cells and lymphocytes, display a constitutive activation of STAT3 due to the stromal paracrine signals in the tumor niche." (PMID 31609088, 2019). "STAT3 activation was demonstrated to drive the proliferation, survival, invasiveness, and metastasis of tumor cells, while strongly suppressing the antitumour immune response." (PMID 30744595, 2019). "Twist1, a basic helix-loop-helix domain-containing transcription factor, promotes tumour metastasis by inducing EMT, and can be upregulated by multiple factors, including SRC-1, STAT3, MSX2, HIF-1α, integrin-linked kinase, and NF-κB." (PMID 31877856, 2019). "To test if blocking of STAT3 phosphorylation by AG-490 can reduce osteolysis and tumor growth in BoM-1833 injected mice, we intrafemorally injected female athymic mice with BoM-1833 cells followed by i.v." (PMID 31040267, 2019).
tumor (continued). "Several anti-apoptosis proteins such as survivin and Bcl-2, which are known to be crucial for tumor survival, represent targets of the transcription factor STAT3 and are down-regulated as a consequence of STAT3 inhibition." (PMID 30914735, 2019). "Enhanced S1PR1 expression activates STAT3 and upregulates IL-6 expression, a proinflammatory cytokine crucial for STAT3 activation and inflammatory cell-mediated transformation and tumor progression." (PMID 31534132, 2019). "Accordingly, STAT3 pharmacological inhibition or downregulation inhibited autophagy and reduced tumor growth both in vitro and in vivo." (PMID 31311917, 2019). "In other tumor samples or experimental tissue culture settings, STAT3 only, or other dual combinations of activated STAT1/3/5, are described." (PMID 31694222, 2019). "STAT3 is a crucial factor in tumor progression and metastasis via the up-regulation of downstream genes such as MMPs and VEGF." (PMID 30041514, 2019). "Tumor development is involved with some signaling pathways of the inflammatory response, such as the activation of transcription factors, including STAT3 and NF-kB, which are activated by growth factors." (PMID 31528182, 2019). "In the present study, we found that an IL-17a neutralizating antibody partly suppressed the JAK2 or STAT3 phosphorylation, which suggested that IL-17a partially contributed to the tumor-promoting effects of TANs on GC cells." (PMID 30616627, 2019). "Alternatively, the signal transducer and activator of transcription 3 (STAT3) factor is found to be overexpressed in various cancers where it favours tumour growth and progression." (PMID 31003534, 2019). "In this context, the BCR-ABL/STAT3/STAT5 signaling pathway is mainly involved in tumor-initiating stem cell maintenance." (PMID 31861612, 2019). "HBx-induced upregulation of miR-21 by Il-6 mediated STAT3 signaling typically blocks tumor suppressors like PTEN and PDCD4 at an early stage in the inflammation–fibrosis axis and continues in the HBV-HCC stage (pathway 14)." (PMID 31771261, 2019). "Western blotting was used to detect the expression of STAT3 protein in tumor tissues of TCSS patients." (PMID 31270251, 2019). "Systemic administration limits its effectiveness in solid tumors, but a Phase I study did show inhibition of the target STAT3 and reduced tumor growth in Diffuse Large B-Cell Lymphoma." (PMID 31803140, 2019). "At the same time, STAT3 phosphorylation is critically associated with GSC phenotypes and immune evasion by regulating the tumor microenvironment contributing to tumor recurrence and resistance to standard treatment." (PMID 31698775, 2019). "G-CSF activates STAT3 in these receptor-positive CSCs; this signaling promotes stemness maintenance, clonal expansion, tumor formation and dissemination, and chemoresistance." (PMID 31867574, 2019). "The delivery of nanovaccines containing cytosine-guanine oligodeoxynucleotides, STAT3 siRNA, and tumor-specific antigens to DCs significantly enhanced the CD8+ T cell responses and inhibited tumor growth." (PMID 30658461, 2019). "STAT3 (also known as acute phase response factor) is DNA-binding, an intracellular signaling protein that has pleiotropic effects on embryogenesis, oncogenesis, tumor suppression, cell differentiation, growth, and both innate and adaptive immunity." (PMID 31105556, 2019). "The inhibition of tumor growth in xenografted nude mice and downregulated p-STAT3(Tyr705) and survivin in tumor tissues was also reported in this study." (PMID 31261861, 2019). "Overall, aberrant activity STAT3 have been described as a contributing factor for the formation of a tumor, chemoresistance, and poor prognosis in HNSCC." (PMID 31575007, 2019). "Abnormal activation of the JAK2/STAT3 pathway plays critical roles in tumor cell proliferation, invasion, survival, angiogenesis and immunosuppression." (PMID 30857539, 2019).
tumor (continued). "Mechanistically, it was established that CD86-CTLA4 engagement resulted in recruitment/activation of TYK2, which, in turn, led to a STAT3-driven tumor-promoting transcriptional program." (PMID 31694222, 2019). "IL-8 has also been recently reported to be a CAA activator, as its ectopic expression has been described to activate tumor-counterpart adipocytes and to enhance their pro-tumorigenic functions in a STAT3-dependent manner." (PMID 31569710, 2019). "It was further shown that NKTL tumours with high expression of phosphorylated STAT3 correlated significantly with PD-L1 levels highlighting its clinical importance in immune checkpoint inhibition." (PMID 30876435, 2019). "Aberrant activation of STATs, especially STAT-3, contributes to tumor progression at several levels." (PMID 30373171, 2018). "It has already been shown that ANXA2 can activate STAT3 in macrophages and promote tumour formation." (PMID 30050103, 2018). "It demonstrates that STAT3 signaling is a core pathway mediating human immune suppression in the tumor microenvironment." (PMID 29951542, 2018). "Activated Stat3 regulates tumour invasion by regulating the gene transcription of matrix metalloproteinase 2 (MMP-2), MMP-9, TGF-β1 and β-catenin, which also decreased after treatment with MSC-CM." (PMID 30297887, 2018). "Since both the pY705 and pS727 sites of STAT3 regulated GIC function in vitro, we injected GBMX16 GICs harboring these STAT3 phosphorylation-defective mutants subcutaneously into the flanks of mice, and tumor growth was monitored by live animal imaging." (PMID 29774125, 2018). "Exposure to Gef results in the feedback activation of STAT3, which is known to promote tumor cell survival under conditions of stress." (PMID 29942660, 2018). "As an important transcriptional promoter, STAT3 is involved not only in the pathogenesis and sustainable development of many malignancies but also in the induction and maintenance of tumor immune tolerance." (PMID 30176876, 2018). "Accumulating data showed that sorafenib and its derivatives can effectively suppress tumor of HCC through SHP1/STAT3 axis." (PMID 29558404, 2018). "According to some reports, STAT3 is constitutively activated in cancer cells as well as tumor‐infiltrating immune cells, including TAMs,30 resulting in suppression of pro‐inflammatory cytokine and chemokine production." (PMID 30311406, 2018). "Recent studies have implied that inhibition of STAT3 signalling can inhibit tumor growth, re-sensitize them to therapy, and induce apoptosis under both in vitro and in vivo conditions." (PMID 30217007, 2018). "STAT3 is known to act through its ability to regulate both oncogenes and tumor suppressor genes, as well as influencing tumor microenvironments." (PMID 29588647, 2018). "STAT3 activation also contributes to pathological processes as oncogenesis, by augmenting tumor invasion and angiogenesis." (PMID 29703138, 2018). "HIF1α, another STAT3-dependent gene, mediates the differentiation into tumor-infiltrating macrophages." (PMID 30075733, 2018). "Recently, another IL-6 cytokine family member, IL-11 was observed in high abundance in CRC tumor samples and correlated with increased phosphorylated STAT3 levels." (PMID 30572654, 2018). "In GI cancers, the activation level of STAT3 seems to be of importance with regard to increasing tumor size and proliferation in mouse models, and IL-6 seems to be the most important activator of the STAT3-cascade." (PMID 30038723, 2018). "Disruption of STAT3 signaling leads to the inhibition of growth and apoptosis in tumor cell lines and can impair tumor growth in the mouse." (PMID 30199527, 2018). "Inhibition of tumor growth by HCMV resulted from restricted STAT3 activation and specific activation of the intrinsic apoptotic pathway." (PMID 30081496, 2018).